ANGPT2 (angiopoietin 2)
Diseases named in the same sentence as ANGPT2 in open-access papers (continued):
Sharing a sentence is not in itself a finding about the gene and the disease.
prostate carcinoma (3 papers, 2012 to 2022). A carcinoma that arises from epithelial cells of the prostate gland. "Angpt2 expression is strongly correlated with prostate cancer progression and is stimulated by growth factors, especially VEGF; Vegf expression is stimulated by androgen treatment in fetal prostate fibroblasts, but we did not observe an effect of estrogen on Vegf expression here." (PMID 23144751, 2012). "In particular, ANGPT2, CYR61 and VEGFC are involved in angiogenesis and are up-regulated in prostate cancer." (PMID 22328933, 2012).
renal fibrosis (3 papers, 2023 to 2024). A final common manifestation of a wide variety of chronic kidney diseases characterized by glomerulosclerosis and tubulointerstitial fibrosis. "A previous study has shown that ANGPT2 was identified as an important mediator of renal fibrosis and autophagy in diabetic nephropathy, and its knockdown increased autophagy and reduced renal fibrosis by activating the MEK/ERK/Nrf-1 pathway." (PMID 38808888, 2024). "ANGPT2 was identified as a significant mediator of renal fibrosis and autophagy in diabetic nephropathy, whose knockdown increased autophagy level and attenuated renal fibrosis via activating the MEK/ERK/Nrf-1 pathway." (PMID 36272879, 2023). "Because the abnormal increase of Angpt2 expression promotes the migration of endothelial MCP-1 activated macrophages and cell death in renal fibrosis, L1-10 can indirectly reduce the expression of MCP-1 by inhibiting Angpt2 to protect the kidney." (PMID 37861543, 2023).
Shock (3 papers, 2015 to 2021). The state in which profound and widespread reduction of effective tissue perfusion leads first to reversible, and then if prolonged, to irreversible cellular injury. "Fisher and colleagues found that higher plasma baseline levels of angiopoietin-2 were significantly associated with fluid overload, an index of microvascular permeability and leakage, within the first six hours in patients with development of septic shock." (PMID 33541396, 2021). "Treatment of AE-IPF or septic shock with PMX-DHP has also been reported to decrease the concentrations of serum matrix metalloproteinase (MMP)-9, vascular endothelial growth factor (VEGF), and angiopoietin-2, which can facilitate vascular permeability." (PMID 25887940, 2015).
uveal melanoma (3 papers, 2021 to 2025). A melanoma derived from melanocytes of the uveal tract. "These uveal melanoma patients exhibit an increase in the expression of classic and well-documented hypoxia-dependent genes such as PDGFB, LOXL2, VEGF, ANGPT2, KDR, and S1PR1." (PMID 40000790, 2025). "We hypothesize that proangiogenic factors such as angiopoietin-1 (ANG-1) and angiopoietin-2 (ANG-2), two targetable cytokines, may play a role in tumor development in uveal melanoma." (PMID 34439141, 2021).
vivax malaria (3 papers, 2014 to 2021). "Severe vivax malaria was associated with increased angiopoietin-2 and impaired microvascular reactivity." (PMID 25569250, 2015). "In vivax malaria, urinary GAGs correlated with angiopoietin-2 (r = 0.41, p = 0.003), ADMA (r = 0.40, p = 0.004), and ICAM-1 (r = 0.54, p < 0.0001), with the correlation with ADMA and ICAM-1 remaining significant after adjusting for parasitemia (p = 0.0001)." (PMID 33963210, 2021). "Syndecan-1 also correlated with endothelial activation (ICAM-1, angiopoietin-2) and ADMA in vivax malaria." (PMID 33963210, 2021).
acute lung injury (2 papers, 2018 to 2022). A condition of lung damage that is characterized by bilateral pulmonary infiltrates (pulmonary edema) rich in neutrophils, and in the absence of clinical heart failure. "Together with ANGPT2, vWF is frequently regarded as a marker for endothelial damage and higher soluble plasma levels are correlated with increased mortality in acute lung injury." (PMID 30574096, 2018).
ANCA-Associated Vasculitis (2 papers, 2012 to 2021). "In addition, serum levels of angiopoietin-2 were significantly elevated in ANCA-associated vasculitis with renal involvement compared to patients with active limited granulomatous disease restricted to the respiratory tract or healthy subjects." (PMID 33541396, 2021).
angiosarcoma (2 papers, 2013 to 2023). A malignant tumor arising from the endothelial cells of the blood vessels. "In the case of reduced or absent CD31 immunoreactivity in a suspected hemangiosarcoma, additional immunohistochemistry can be performed, including von Willebrand factor, vascular endothelial growth factor A, or angiopoietin-2." (PMID 37104402, 2023). "Strong expression of ANGPT2, TIE1, and TEK mRNAs has been reported in cutaneous angiosarcomas, and Tie2 antagonists inhibit in vitro angiosarcoma cell survival and delay in vivo angiosarcoma tumor growth." (PMID 25374893, 2013). "Indeed, compared to other sarcomas, angiosarcoma tumors exhibited higher expression levels of endothelial marker/functional genes including PECAM1, EPHA2, ANGPT2, ENDRB, PGF, FLI1, VWF and reduced expression levels in KIT, VEGFA, and VEGFB." (PMID 25374893, 2013).
asthma (2 papers, 2016 to 2024). "We found positive association of Angiopoietin-2 levels with asthma exacerbation defined as unscheduled visits in the clinic, emergency interventions or hospitalization." (PMID 26937244, 2016). "Increased serum levels of proangiogenic Angiopoietin-2 in asthmatics and its association with clinical markers of asthma severity, including exacerbations, may reflect ongoing airway inflammation." (PMID 26937244, 2016). "Significantly elevated levels of angiopoietin-2 were observed in individuals with asthma compared to healthy subjects, and these levels correlated with the severity of asthma." (PMID 38562155, 2024). "Angiopoietin-2 correlated also with BMI of patients (R = 0.33; p < 0.001) and duration of the asthma (R = 0.2; p < 0.05)." (PMID 26937244, 2016). "For the whole asthma group inverse correlation of serum Angiopoietin-2 levels with respiratory function parameters: FEV1% of predicted value (R = −0.31; p < 0.05) FEV1/FVC value (R = −0.21; p < 0.05) and MEF 25-75 (R = −0.27; p < 0.01) was found." (PMID 26937244, 2016). "These patients, who fulfilled the ATS criteria for SRA, had significantly increased Angiopoietin-2 levels as compared to the patients with mild/moderate asthma." (PMID 26937244, 2016). "Angiopoietin-2 seems to be a crucial proangiogenic cytokine overproduced in patients with SRA characterized by repeated exacerbations and Angiopoietin-2 serum levels can serve as a biomarker of severe asthma." (PMID 26937244, 2016). "Further studies are required to assess if Angiopoietin-2 serum level can serve as a biomarker of asthma severity and remodeling." (PMID 26937244, 2016). "Interestingly, Angiopoietin-1 and Angiopoietin-2 levels were recently detected to be upregulated in the induced sputum from patients with optimally treated asthma, and seemed to be also related to the smoking status." (PMID 26937244, 2016). "In an earlier study Angiopoietin-2 rather than Angiopoietin-1 was associated with asthma and Angiopoietin-1/Angiopoietin-2 ratio was positively correlated with lung function in adult asthma patients." (PMID 26937244, 2016). "When asthmatics were stratified according to the severity, the mean serum level of Angiopoietin-2 was found to be significantly higher in patients with SRA as compared to nSA (6.04 ± 0.46 vs 3.84 ± 0.43; p < 0001), and in both asthma groups mean Angiopoietin-2 levels were higher as compared to HC." (PMID 26937244, 2016). "In our study the increased Angiopoietin-2 concentrations constituted a significant risk factors for the severe asthma comparable to total IgE or ECP levels in serum, which are well documented asthma severity markers." (PMID 26937244, 2016). "Thus, it is likely that the association of increased serum levels of Angiopoietin-2 with the rate of asthma exacerbation may reflect a direct or non-direct release of proangiogenic factors in the airways by respiratory pathogens." (PMID 26937244, 2016). "Moreover, Angiopoietin-2 serum levels correlated with several clinical features of asthma severity and control including chronic dose of inhaled glucocorticosteroids, number of asthma exacerbations, emergency room interventions and even number of hospitalizations during the preceding year." (PMID 26937244, 2016). "Patients with asthma, regardless of the diseases severity had on average almost threefold higher mean Angiopoietin-2 serum levels and significantly increased Angiopoietin-1 and VEGF serum concentrations, reflecting probably ongoing angiogenesis in the airways." (PMID 26937244, 2016). "In our study proangiogenic factors other than Angiopoietin-2, did not correlate so well with asthma phenotypes." (PMID 26937244, 2016). "Serum concentrations of Angiopoietin-2, VEGF, Angiopoietin-1 and osteopontin did not correlate with classical markers of asthma severity or asthmatic inflammation: blood eosinophil number and serum ECP or total IgE levels." (PMID 26937244, 2016).
bladder cancer (2 papers, 2020 to 2022). "Consistent with previous studies, we also found that AnxA2 knockdown significantly inhibited bladder cancer cell proliferation, migration, and invasion, along with remarkably decreased expression of proangiogenic proteins such as PDGF-BB, ANGPT1, ANGPT2, Tie-2, bFGF, GRO, IL-6, IL-8, and MMP-9." (PMID 36428758, 2022). "In addition, the downregulation of AnxA2 cells significantly inhibited the proliferation, migration, and invasion in bladder cancer along with the reduction in proangiogenic factors and cytokines such as PDGF-BB, ANGPT1, ANGPT2, Tie-2, bFGF, GRO, IL-6, IL-8, and MMP-9." (PMID 36428758, 2022).
brain cancer (2 papers, 2011 to 2019). A primary or metastatic malignant neoplasm affecting the brain. "ANGPT1 and ANGPT2 contribute to the glucose metabolism by interacting with VEGF and they are both indicated to have a prognostic value in adult forms of malignant brain tumors." (PMID 21726470, 2011).
capillary leak syndrome (2 papers, 2021 to 2026). A syndrome characterized by leakage of intravascular fluids into the extravascular space. "As a marker of vascular integrity, angiopoietin-2 may therefore be associated with the presence of edema reflecting conditions with unfavorable prognosis such as capillary leak syndrome or edema of the brain in post-cardiac arrest patients." (PMID 33976254, 2021). "Transfusions were associated with modest increases in extracellular water and elevated serum levels of angiopoietin-2 and syndecan-1, consistent with Capillary Leak Syndrome, although absolute ECW differences were small." (PMID 41938900, 2026).
cardiac arrest (2 papers, 2021). Cessation of breathing and/or cardiac function. "This is likewise underlined by angiopoietin-2 data from cardiac arrest patients, where imbalances in angiopoietin ratios (angiopoetin-1/angiopoetin-2) were associated with organ dysfunction and poor outcome." (PMID 34179033, 2021).
cerebral infarction (2 papers, 2022 to 2025). An ischemic condition of the brain, producing a persistent focal neurological deficit in the area of distribution of the cerebral arteries. "This was significantly lower than that in the BSA-MCAO group of 9.07 ± 1.49 mm3, suggesting that Angpt2 could significantly reduce cerebral infarction caused by ischemic injury." (PMID 36358355, 2022). "Furthermore, Beclin1 knockdown significantly increased the levels of angiopoietin-2 (ANG-2) and vascular endothelial growth factor (VEGF) in the ipsilateral thalamus after cerebral infarction." (PMID 40735300, 2025).
Chronic Hepatitis C (2 papers, 2013 to 2023). "The association of angiopoietin-2 levels with chronic CMV and EBV infections has not been reported before, but increased angiopoietin-2 levels have been related to chronic hepatitis C infection." (PMID 38012652, 2023).
chronic lymphocytic leukemia (2 papers, 2019 to 2025). "Concerning ANGPT2, the methylation status of 6 CpGs near the gene transcription site (four of which were analyzed in this study) has already been shown to predict overall survival of chronic lymphocytic leukemia patients." (PMID 31069961, 2019). "ANGPT2 promoter does not contain a CpG island; therefore, we analyzed single CpGs shown to be hypomethylated in 4C11+ cells and that had also been previously evaluated in chronic lymphocytic leukemia." (PMID 31069961, 2019).
chronic obstructive pulmonary disease (2 papers, 2012 to 2021). A chronic and progressive lung disorder characterized by the loss of elasticity of the bronchial tree and the air sacs, destruction of the air sacs wall, thickening of the bronchial wall, and mucous accumulation in the bronchial tree. "Moreover, ANGPT2 was upregulated in chronic obstructive pulmonary disease (COPD) patients with PAH." (PMID 34016786, 2021).
clear cell renal cell carcinoma (2 papers, 2019 to 2025). "For instance, in renal clear cell carcinoma endothelial-like genes such as ANGPT2 and VWF were notably upregulated, whereas OCLN levels were significantly decreased." (PMID 40083695, 2025). "Interestingly, our meta-analysis also indicated a trend of ANGPT2 upregulation across several cancer types, including colon, esophageal, glioblastoma, stomach, hepatocellular, and renal clear cell carcinomas, suggesting its involvement in tumour progression." (PMID 40083695, 2025).
coagulopathy (2 papers, 2017 to 2026). "The present report supplements our earlier reports regarding angiopoietin-2 and sFlt-1 as the markers of severity in AP; hereby we show (pathophysiologically relevant) associations of these endothelial markers with coagulopathy in AP." (PMID 28368336, 2017).
colitis (2 papers, 2018 to 2024). Inflammation of the colon. "Blocking lymphangiogenesis through vascular growth factor receptor 3-blocking antibodies or angiopoietin 2 deficiency has been shown to aggravate intestinal inflammation in colitis mice." (PMID 38785804, 2024).
dementia (2 papers, 2022 to 2024). Loss of intellectual abilities interfering with an individual's social and occupational functions. "In this study, CSF ANGPT-2 level was highest in MCI patients and correlated with CSF albumin and sPDGFRβ, a marker of pericyte injury that was previously shown to be elevated in early AD (clinical dementia rating 0.5) and to correlate with MRI evidence of BBB breakdown within the hippocampus." (PMID 38182581, 2024).
diabetic eye disease (2 papers, 2022 to 2023). A group of disorders affecting the eye in patients with diabetes mellitus. "Faricimab, a novel bispecific antibody, provides dual inhibition of both VEGF-A, and angiopoietin-2 (Ang-2) to treat vascular eye diseases, including diabetic eye disease." (PMID 36589807, 2022). "ANGPT2 and VE-PTP, two emerging targets for the treatment of diabetic eye disease, are both expressed specifically by vascular cells." (PMID 37227777, 2023).
edema (2 papers, 2022 to 2023). An abnormal accumulation of fluid beneath the skin, or in one or more cavities of the body. "We are not aware of any other biallelic ANGPT2 LOF variants in other cohorts of fetal hydrops to date, and no other match for ANGPT2 was identified via GeneMatcher." (PMID 34876502, 2023). "We noted no specific feature that distinguishes ANGPT2-related hydrops from other forms of NIHF." (PMID 34876502, 2023).
fetal growth restriction (2 papers, 2024 to 2025). A fetus that does not grow beyond the 10th percentile of conventionally accepted weight for gestational age. "Tight regulation of angiopoietin-2 mediates placental vascular remodelling and its dysfunction contributes to placental perturbations and hypoxia; in sheep and humans, late gestation placental expression of ANGPT2 mRNA and protein is reduced in response to fetal growth restriction." (PMID 41204352, 2025). "Notably, both the ovine model and human studies found that the angiopoietin-2/Tie-2 pathway plays a fundament role in the development of the placenta, and an altered angiopoietin-2/Tie-2 pathway may lead to intrauterine growth restriction." (PMID 39090584, 2024).
Hepatic failure (2 papers, 2021 to 2024). "Plasma angiopoietin-2 levels were also associated with hepatic failure, coagulation failure, circulatory failure and the overall number of organ dysfunctions." (PMID 33541396, 2021). "Higher plasma angiopoietin-2 levels by quartile were significantly associated with hepatic failure (p < 0.001), coagulation failure (p < 0.001), and circulatory failure (p = 0.003) as defined by Brussels organ failure scores." (PMID 33541396, 2021).
infantile hemangioma (2 papers, 2013 to 2016). "Interestingly, some of these genes also play roles in cell signaling pathways that have been linked to the pathogenesis of infantile hemangioma; namely, VEGFA in the VEGF/VEGFR pathway, ANGPT2 and ANGPTL1 in the Tie2/Angiopoietin signaling pathway and NOTCH3, NOTCH4 and JAG1 in the Notch pathway." (PMID 26772808, 2016).
kidney damage (2 papers, 2021 to 2022). "In addition, the increased expression of angiopoietin 2, interleukin-6, tumor necrosis factor-α, and endostatin in the blood indicated kidney damage in this model." (PMID 36289909, 2022).
lung disease (2 papers, 2020 to 2021). "Previous studies have reported that Angpt2 gene polymorphisms are associated with sleep-disordered breathing 25 and lung injury syndrome 13, 26, 27, indicating that Angpt2 could be a biomarker for lung disease." (PMID 31929743, 2020). "The present review focuses on the clinical impact of the Angiopoietin-1, Angiopoietin-2, and Angiopoietin-4 levels in patients diagnosed with NSCLC, emphasizing the interaction between them, and how they affect the development, progression, and metastasis of lung disease." (PMID 34833409, 2021).
macular edema (2 papers, 2025). "These conditions are characterized by pathological processes, such as angiogenesis, ocular hemorrhage, and macular edema, all associated with elevated β-catenin, HIF-1α, VEGF, angiopoietin-2, and MCP-1 levels." (PMID 40362263, 2025).
malignant thyroid tumors (2 papers, 2021 to 2025). "It has been determined that ANGPT2 expression can differentiate between benign and malignant thyroid tumors with high sensitivity (100%) but low specificity (77%)." (PMID 40346322, 2025). "A consistent increase in VEGF, VEGF-C, and angiopoietin-2 and their tyrosine kinase receptors VEGFR2, VEGFR3, and TEK receptor tyrosine kinase have been demonstrated in thyroid cancer versus normal thyroid tissues, and a strong correlation has been found between this overexpression and tumor size." (PMID 34204889, 2021).
nasopharyngeal carcinoma (2 papers, 2014 to 2020). A carcinoma arising from the nasopharyngeal epithelium. "For example, endothelial cells are responsible for supporting tumor neovasculature, also participating in several molecular signaling pathways, and HOTAIR has been identified can regulate VEGF-A and angiopoietin 2 (Ang2) expression in nasopharyngeal carcinoma and glioma." (PMID 32951010, 2020).
nephritis (2 papers, 2021). Inflammation of renal tissue. "In our study, we found that Angpt2 expression increased on the 7th day of anti‐Thy‐1 nephritis." (PMID 33987885, 2021). "Therefore, we suspected that MCs‐derived VEGFA and ECs‐derived Angpt2 might play important roles in ECs proliferation of anti‐Thy‐1 nephritis." (PMID 33987885, 2021). "Angiopoietin-2 (Ang2) level was increased in SLE patients in comparison to the control, and it was significantly higher in the LN patients than in SLE patients that did not have nephritis." (PMID 35095896, 2021).
ocular hypertension (2 papers, 2019 to 2023). Abnormally high intraocular pressure. "ANGPT2-clustering antibody treatment was found to increase TEK phosphorylation in aged mice and lower IOP in an injury-induced model of ocular hypertension." (PMID 31621585, 2019).